ATF6 (activating transcription factor 6)
Diseases named in the same sentence as ATF6 in open-access papers (continued):
Sharing a sentence is not in itself a finding about the gene and the disease.
viral infection (19 papers, 2007 to 2025). "Virus infection caused a greater reduction in ATF6 level at this time." (PMID 29386036, 2018). "We previously demonstrated that PPRV infection induces ER stress and selectively activates the ATF6 pathway of the UPR to promote viral infection in Vero cells." (PMID 38812563, 2024). "Previous studies suggested that virus infection results in a selective induction of ATF6-regulated UPR pathway." (PMID 32753633, 2020). "In cells transfected with full-length ATF6, the serial cleavage products N-45, C-50, and C-25 were detected during viral infection." (PMID 29386036, 2018). "Two fragments, C-50 and C-25 (indicated by asterisks in lane 6), were produced from Wt ATF6, but only C-50 was detected in the G512/G517 mutant upon viral infection (lanes 6–7)." (PMID 29386036, 2018). "To examine the possible cleavage pattern during viral infection, we transfected HA-ATF6(1-516aa)-FLAG into HEK293T cells to improve the efficiency of ATF6 expression." (PMID 29386036, 2018). "A time course of infection revealed that the reduction in ATF6 became evident at 4 h p.i. and was more prominent with increasing length of viral infection in the scrambled and siXBP1-transfected cells (lanes 10 and 12)." (PMID 29386036, 2018). "This idea was supported by observations showing that ATF6 signaling was stimulated by virus infections, such as HCV and African swine fever virus (ASFV), and beneficial to viral replication." (PMID 28832521, 2017). "Although ATF6-mediated transcriptional activation is an ongoing research field, another role for ATF6 in virus infection has emerged." (PMID 25140166, 2014). "It would be interesting to investigate the role of viral 3C in the regulation of ATF6, for its possible contribution in manipulating virus infection." (PMID 25140166, 2014). "The ATF6 pathway is also targeted by several viral infections." (PMID 40248709, 2025). "It is known that in the process of virus infection, the endoplasmic reticulum (ER) loses its homeostasis, inducing stress and the subsequent unfolded protein response or UPR in which three ER-trans-membrane proteins are implicated: PERK, IRE1 and ATF6." (PMID 39772156, 2024). "Our findings indicate that ATF6 plays a distinct role in viral protein stability and that the host uses different cleavage strategies, rather than conventional cleavage by generating p50ATF6, to combat viral infection." (PMID 29386036, 2018). "This suggested first that Dengue serotypes may selectively modulate ATF6 activation to either inhibit aspects that could be deleterious to the progress of the viral infection or enhance host's ability to favor it." (PMID 17888185, 2007). "Depending on the type of virus infection, 3 major UPR response pathways can be activated, namely, PKR-like ER kinase (PERK), inositol-requiring enzyme 1 (IRE1), and activating transcription factor 6 (ATF6)." (PMID 35951530, 2022). "Thus, the recovery of the ATF6, eIF2α and PERK pathways allows the cell to activate multiple infection response pathways, some as efficient as autophagy in the fight against viral infections." (PMID 38612846, 2024). "The results showed that EDEM1 gene, calreticulin, and calnexin mRNA levels were all not modified in cp BVDV-infected MDBK cells, indicating that viral infection did not activate the ATF6 and XBP1 signaling pathways." (PMID 36939351, 2023). "Under some conditions that may induce ER stress, such as viral infection and tumorigenesis, GRP78 dissociates from the transmembrane stress sensor proteins PERK, IRE1, and ATF6 and acts as a repressor of the unfolded protein response." (PMID 35923704, 2022). "Moreover, viral infection induces ER stress, and hence induces both GRP78/BiP and ATF6α to facilitate protein folding during viral maturation." (PMID 23716639, 2013).
viral infection (continued). "The ATF6 pathway is presumably activated during viral infection, as suggested by the proteolytic cleavage of p90ATF6, whereas the production of the active p50ATF6 fragment and the activation of its downstream target gene BiP in an ATF6- and ERSE-dependent manner do not occur." (PMID 29386036, 2018).
hepatoma (18 papers, 2013 to 2025). "In hepatitis B virus (HBV)‐infected hepatoma cells, ethanol‐induced ER stress activates ATF6 and IRE1α, disrupting HBV core peptide–MHC‐I transport and impairing CD8+ T cell recognition." (PMID 40547943, 2025). "In general, PPM1H, as a downstream gene of ATF6, has a suppressive effect on the growth of hepatoma cells." (PMID 37456776, 2023). "In the present study, we identified that expression of protein phosphatase magnesium- or manganous-dependent 1H (PPM1H) mRNA and protein can be inhibited by ATF6 in hepatoma cells and mice with liver Atf6 knockdown." (PMID 37456776, 2023). "Similar results were obtained when ATF6α was overexpressed in HepG2 cells (human hepatoma cell line)." (PMID 23716639, 2013). "Consistently, in PPM1H knockdown cells, co-transfecting ATF6 plasmids barely altered the migration and invasion of Hep-G2 and Huh-7 cells, indicating that ATF6 regulates the proliferation and metastasis of hepatoma cells through the function of PPM1H." (PMID 37456776, 2023). "In addition, in hepatoma cell lines, ATF6 and PGC-1α activities enhance estrogen-related receptor gamma (ERRγ) expression." (PMID 35225153, 2022). "Moreover, the ATF6 branch was activated by the HCV core protein in a human hepatocellular carcinoma cell line." (PMID 36192392, 2022). "A recent study has also shown that ATF6 branch activation by HBx is essential for host cell survival in hepatoma cells, which could represent a key player in hepatocellular carcinoma development." (PMID 36192392, 2022). "In rat hepatocytes, the UPR signaling molecule involved in the proapoptotic actions of diclofenac was the CHOP protein, but in the Huh7 hepatoma cells the drug also reduced the expression of ATF6 and evoked phosphorylation of eIF2alpha, a protein directly activated by PERK." (PMID 35684385, 2022). "Elevated expression of ATF6α is observed in human hepatocellular carcinoma." (PMID 28860159, 2017). "It has been shown to selectively inhibit ATF6 thereby downregulate ATF6α expression, decrease cyclooxygenase‐2 (COX‐2) levels, and promote apoptosis of hepatoma cells under ER stress." (PMID 40547943, 2025). "Functionally, in hepatoma cells, TMEM166 deletion promotes cell proliferation via the PERK–ATF4 axis and confers sorafenib resistance via IRE1 and ATF6 activation." (PMID 41193471, 2025). "Melatonin selectively inhibited ATF6 and thus COX-2, enhancing endoplasmic reticulum stress-induced apoptosis in human hepatoma cells." (PMID 38641695, 2024). "With respect to the roles of other ER stress effectors of IRE1α and ATF6 in RIBE, our results showed that IRE1α was obviously increased after thapsigargin treatment but attenuated since BiP depletion after receiving the ICCM from irradiated hepatoma cells." (PMID 27958308, 2016). "Also, activation of GPR78/BiP, XBP1 and ATF6 were observed in hepatocellular carcinoma cell line compared to non-cancerous liver tissues." (PMID 30081573, 2018).
Hyperglycemia (18 papers, 2015 to 2025). An increased concentration of glucose in the blood. "The results showed that hyperglycemia-triggered ATF6-CHOP inhibited β-catenin signaling, and CHOP deficiency accordingly effectively restored hyperglycemia-inhibited β-catenin expression." (PMID 35289326, 2022). "In Akita mice, loss of ATF6 accelerates hyperglycemia and β cell loss, indicating that ATF6 pathway is protective in response to Akita proinsulin." (PMID 34943844, 2021). "We previously found that hyperglycemia aggravates acute liver injury via the ATF6 (Activating Transcription Factor 6)‐CHOP (C/EBP‐homologous protein) pathway." (PMID 40778489, 2025). "In summary, UPR sensors, increased MG and MG-modified proteins are major activators of IRE1α, PERK and ATF6 in hyperglycemia." (PMID 38199038, 2024). "The hyperglycemia-triggered ATF6-CHOP pathway was also shown to regulate innate immune responses, and NF-κB and Akt activity in a β-catenin-dependent manner." (PMID 35289326, 2022). "To determine the in vivo relevance of these results, we evaluated sXBP1 and cl-ATF6 α levels in the brachiocephalic artery of ApoE−/− mice with persistent hyperglycaemia or hyperlipidaemia." (PMID 35889743, 2022). "The current study demonstrated that hyperglycemia specifically activated the ATF6-CHOP pathway of ER stress in liver tissues and KCs in DM patients and hyperglycemic mice." (PMID 35289326, 2022). "Collectively, based on the current results we propose that impaired insulin signalling coupled with hyperglycaemia directly impedes sXBP1 activity in podocytes, thus exacerbating ATF6-dependent maladaptive ER response and DN." (PMID 25754093, 2015). "The data showed high glucose and lipids mixture induced ER stress (PERK, CHOP, IREA, Xbp1, and ATF6), inflammation (iNOS and Cox2), and anti-angiogenic factors (Tbsp1), suggesting that in type 2 diabetes, hyperglycemia and hyperlipidemia contribute to the immune cells' dysregulation." (PMID 38094119, 2023). "In response to hyperglycemia, ROS are released into the ER, leading to ER stress by activating three independent ER stress sensors: activating transcription factor 6 (ATF6), inositol-requiring enzyme (IER1), and protein kinase R (PKR)-like endoplasmic reticulum kinase (PERK)." (PMID 35163209, 2022). "In the present study, we demonstrated that the hyperglycemia-triggered ATF6–CHOP axis aggravated IR-induced liver injury via inactivation of β-catenin, which in turn promoted TLR4-driven inflammatory responses, while simultaneously repressing Akt signaling molecules in the ischemic liver." (PMID 35289326, 2022). "Similarly, reduced expression levels of ATF6 and sXBP1 coincide with hyperglycemia in both a genetic mouse model (ob/ob) and humans with type 2 diabetes." (PMID 32724824, 2020). "Lowering blood glucose levels with the SGLT2 inhibitor or treatment with TUDCA normalized nuclear levels of sXBP1, ATF6 (50 kDa) and CHOP and reduced albuminuria and indices of DN, demonstrating that the hyperglycaemia-induced maladaptive UPR is causally linked to DN." (PMID 25754093, 2015). "The current study suggested that hyperglycemia could trigger ER stress-ATF6-CHOP axis, inhibit β-catenin activation, accelerate inflammation, and deteriorate liver IRI, thus providing the treatment potential for management of sterile liver inflammation in DM patients." (PMID 35289326, 2022). "The transcriptions of PERK, ATF6 and IRE1 were increased in response to hyperglycemia treatment, suggesting an activation of ER stress." (PMID 32392536, 2020). "β-catenin knockdown restored hyperglycemia-related inflammatory responses and hepatic IRI in CHOP−/− mice in vivo, thus implicating β-catenin as a key regulator of innate immunity in hyperglycemia-triggered ATF6-CHOP promotion of inflammation." (PMID 35289326, 2022).
Hyperglycemia (continued). "Given that hyperglycemia specifically activated the ER stress-ATF6-CHOP pathway and promoted pro-inflammatory responses in hepatic IR injury, we explored whether hyperglycemia had a similar influence on macrophages at the cellular level." (PMID 35289326, 2022). "To determine whether hyperglycaemia is sufficient to cell-autonomously initiate the maladaptive UPR, we determined sXBP1, ATF6 and CHOP levels in glucose-treated podocytes and glomerular endothelial cells (GENCs) in vitro." (PMID 25754093, 2015). "Similarly, HRECs stimulated with TNF + HG treatment demonstrated activation of IRE1α pathway but not PERK and ATF6 suggesting that inflammation and hyperglycemia in endothelial cells results in diverse UPR pathways." (PMID 31346222, 2019). "Interestingly, ATF4 and CHOP, but not ATF6 and s-XBP1, were further enhanced by hyperglycemia compared to the CON group." (PMID 29081777, 2017).
prostate carcinoma (18 papers, 2012 to 2025). A carcinoma that arises from epithelial cells of the prostate gland. "It has been elucidated that elevated ATF6α is closely associated with the progression of prostate cancer." (PMID 39080273, 2024). "These molecules can block S2P cleavage activity to lead to the accumulations of precursor SREBP-1 and ATF6 against castration-resistant prostate cancer." (PMID 35912181, 2022). "However, ATF6 exhibits a tumor suppressor effect when combined treatment with clofoctol and sorafenib in prostate cancer." (PMID 39080273, 2024). "Thus, we provide the novel mechanistic model of ATF6 activation and ER stress implication in the progression of PCa, suggesting ATF6 is a novel promising target for prostate cancer therapy." (PMID 34521429, 2021). "In addition, the functionality of ATF6 is complex and its paradoxical effects in prostate cancer may be related to the pharmacological agents used." (PMID 39080273, 2024). "Interestingly, according to the information from the previous publications, TUSC3 exerts its regulating effects on UPR, and TUSC3-deficiency specifically activates ATF6-branch mediated UPR to promote cancer development and metastasis in prostate cancer and non-small cell lung cancer." (PMID 34381729, 2021). "The study indicated cross talk among GRP78 and NF-κB in prostate cancer cells, and the abrogation of GRP78 blunts the activation of NF-κB through the ATF6 branch of the UPR." (PMID 34769349, 2021). "In liposarcoma and prostate cancer cells, nelfinavir led to the accumulation of sterol regulatory binding protein-1 (SREBP-1) and ER stress protein ATF6." (PMID 33228205, 2020). "At the mRNA level, a time-dependent increase in ER stress-related genes ATF6, GRP78, and XBP-1 was observed during treatment by nelfinavir in castration-resistant prostate cancer cells." (PMID 33228205, 2020). "Western blotting and RT-qPCR analysis revealed that ectopic expression of miR-200c-3p increased the expression of IRE1α, ATF6, and CHOP in PC-3 prostate cancer cells." (PMID 29308051, 2018). "Considering these data, we next investigated whether the NXP800-mediated increase in eIF2α phosphorylation and ATF4, ATF6, and IRE1 protein expression was beneficial or detrimental to these prostate cancer models studied." (PMID 39787247, 2025). "Finally, treatment with 250 nmol/L NXP800, but not its inactive chemical control CCT365248 at this concentration, resulted in increased eIF2α phosphorylation and ATF4, ATF6, and IRE1 protein expression in VCaP, LNCaP95, and 22Rv1 prostate cancer cells." (PMID 39787247, 2025). "In our study, BP induced only IRE1-α activation but not ATF6 or p-eIF2α in prostate cancer cells." (PMID 22470469, 2012). "Consistent with these discoveries, we further confirmed that treatment of VCaP, LNCaP95 and 22Rv1 prostate cancer cells with NXP800, but not the inactive chemical control CCT365248, increased eIF2α phosphorylation and ATF4, ATF6, and IRE1 protein expression." (PMID 39787247, 2025). "Some studies have provided evidence that the decreases in S2P expression, and the absence of mature SREBP1 and ATF6 production, resulting in the failure to activate the UPR, can induce apoptosis in liposarcoma and prostate cancer cells." (PMID 37958642, 2023).
Stroke (14 papers, 2017 to 2024). Sudden impairment of blood flow to a part of the brain due to occlusion or rupture of an artery to the brain. "Evidence points to a consistent over-expression of ATF6 in intracerebral hematoma, suggesting a significant association between ATF6 and stroke." (PMID 38613810, 2024). "Using mice with global deletion of Atf6 (Atf6−/−), a previous study showed that these mice exhibited worse brain damage after stroke." (PMID 38543139, 2024). "It is evident that ATF6 activation represents a promising target in the search for therapies to mitigate the functional consequences of stroke." (PMID 37891634, 2023). "The ratio of cleaved ATF6 to full-length ATF6 demonstrates that Carbamathione increases ATF6 cleavage in PC-12 cells in hypoxia/reoxygenation using the in vitro model of stroke." (PMID 37509524, 2023). "Our research findings highlight the significance of genes associated with the UPR pathway, including ATF6, EXOSC5, EEF2, LSM4, NOLC1, BANF1, and DNAJC3, in the occurrence of stroke." (PMID 37891634, 2023). "The activation of ATF6 in the brain after a stroke has been found to reduce functional brain damage, potentially through the promotion of UPR." (PMID 37891634, 2023). "Method: sATF6-KI mice with functional short-form ATF6 (sATF6) predominantly expressed in forebrain neurons were subjected to two ischemic stroke models: photothrombotic stroke and permanent middle cerebral artery occlusion (pMCAO)." (PMID 36313623, 2022). "Since tamoxifen-induced sATF6 nuclear translocation is transient, we extended the effects of ATF6 activation by dosing tamoxifen every other day from day 4 to day 15 after stroke." (PMID 36313623, 2022). "In the case of glutamate excitotoxicity and stroke, taurine treatment suppresses ATF6 and IRE1 signaling, the same pathways affected by taurine deficiency." (PMID 28757580, 2017). "In the post-stoke setting, elevated autophagic activity levels during early reperfusion time are hypothesized to add to the neuroprotection provided by ATF6, making the ATF6 UPR pathway imperative to stroke outcomes." (PMID 37008060, 2023). "Furthermore, the forced activation of ATF6 in forebrain neurons improved functional recovery in a mouse model of stroke and Huntington’s disease." (PMID 37627643, 2023). "Therefore, to advance translational research on targeting the ATF6 pathway in stroke, new potent and well-characterized ATF6-specific activators are still required." (PMID 36313623, 2022). "Thus, to evaluate the long-term effects of ATF6 activation in permanent stroke, we turned to our pMCAO model." (PMID 36313623, 2022). "Thus, given the large number of stroke patients with permanent vessel occlusion as well as the encouraging data for ATF6 activation in transient brain ischemia models, this study was designed specifically to examine the effects of ATF6 activation in permanent stroke." (PMID 36313623, 2022). "As compared to the stroke group, MPostE and IPostE significantly decreased expressions of GRP78, IRE1α, PERK, ATF6, CHOP, and Caspase-12 (n = 7 respectively)." (PMID 33664650, 2021). "We showed in our experiment that the ratio of cleaved ATF6 to full-length ATF6 indicates that G-CSF decreased ATF6 cleavage in the Frontal and Middle brain samples using the BCAO stroke model." (PMID 31907023, 2020). "Moreover, activating transcription factor 6 (ATF6), one of the signal transduction pathways of UPR, has been reported to modulate the occurrence of autophagy in stroke, but the specific signaling mechanism is still puzzling." (PMID 33688357, 2020). "Previous reports on ER stress in stroke did not assess the cleavage of ATF6 that leads to its nuclear localization and induction of its effects." (PMID 28640888, 2017).